WNT5A (Wnt family member 5A)
Diseases named in the same sentence as WNT5A in open-access papers (continued):
Sharing a sentence is not in itself a finding about the gene and the disease.
metastatic melanoma (8 papers, 2009 to 2021). A melanoma that has spread from its primary site to another anatomic site. "Immunohistochemical analyses have revealed that most metastatic melanoma exhibited strong WNT5A staining comparing to benign tumors and a high WNT5A level in metastatic cutaneous melanoma is associated with poor outcome." (PMID 32659938, 2020). "As Wnt5a is a robust marker of aggressive and metastatic melanoma, our finding of modulation of Wnt5a modification by reprogrammed lipid metabolism provides an essential mechanism of linking metabolism with signaling pathways." (PMID 37849907, 2021). "The tyrosine kinase receptor ROR2, which is predominantly expressed in metastatic melanoma, has been shown to specifically interact with Wnt5a and mediate Wnt5a signaling." (PMID 29648538, 2018). "ROR2, an orphan tyrosine kinase receptor known to mediate Wnt5A signaling, is upregulated in metastatic melanoma cells with high Wnt5A." (PMID 24281103, 2010).
chronic obstructive pulmonary disease (7 papers, 2020 to 2023). A chronic and progressive lung disorder characterized by the loss of elasticity of the bronchial tree and the air sacs, destruction of the air sacs wall, thickening of the bronchial wall, and mucous accumulation in the bronchial tree. "Reduction in both canonical and non‐canonical Wnt5a signalling is linked to impaired lung repair in chronic obstructive pulmonary disease." (PMID 32391621, 2020). "In addition, Wnt5a is reported to be increased in experimental and human chronic obstructive pulmonary disease (COPD) and to induce production of inflammatory cytokines such as IL-6 and TNF-α." (PMID 38062395, 2023).
COVID-19 (7 papers, 2021 to 2024). A disease caused by infection with severe acute respiratory syndrome coronavirus 2. "According to this report, Wnt5a level was significantly higher and Wnt11 level was significantly lower in patients with severe or fatal COVID-19." (PMID 38584257, 2024). "A recent study focused on the radiopathological features of patients with COVID-19-related mediastinal emphysema and discussed the possible role of Sonic hedgehog and Wnt5a pathways in it." (PMID 39057037, 2024). "Having found that anti-inflammatory sFRP5 is increased in DPP4i treated T2D subjects we next examined, if sFRP5 and Wnt5a are altered in COVID-19 patients." (PMID 36056109, 2022). "We observed significant lower sFRP5 levels in COVID-19 patients compared to healthy controls, while Wnt5a levels were significantly increased in COVID-19 patients." (PMID 36056109, 2022). "Most recently, Wnt5A has been found significantly elevated in severe cases of COVID-19, and endotheliitis was observed as major pathology in severe COVID-19." (PMID 34079452, 2021). "Indeed, the complement system was shown to be hyperactivated in severe SARS-CoV-2 infections; SARS-CoV-2 induces DNA damage; and WNT5A is upregulated in severe cases of COVID-19." (PMID 38981682, 2024). "Moreover, Wnt5a levels were significantly increased in COVID-19 patients compared to healthy controls (p < 0.001)." (PMID 36056109, 2022). "Interestingly, Wnt5a and Wnt11 have been suggested to be potential biomarkers of COVID-19 severity, with high levels of Wnt5a correlated to poor prognosis and increased Wnt11 expression indicating efficient inhibition of inflammatory responses caused by SARS-CoV-2 infection." (PMID 38203386, 2023). "Furthermore, it might be of interest how sFRP5/wnt5a levels act in subjects with mild COVID-19 to prevent a possible more severe course of disease or post covid-19 symptoms." (PMID 36056109, 2022). "Our study shows for the first time that Wnt5A induces the gene expression of CYP1A1 and CYP1B1 enzymes involved in phase I metabolism of a broad spectrum of drugs including chloroquine (the controversial drug for COVID-19) that is known to cause toxicity in myocardium." (PMID 34079452, 2021). "Regarding to our findings, a recent study has shown the relation of canonical Wnt/β-catenin pathway with inflammatory responses, which is based on the observation of Wnt5a and Wnt11, as ARDS biomarkers, released from immune cells in patients with COVID-19." (PMID 38584257, 2024).
esophageal cancer (7 papers, 2012 to 2025). A primary or metastatic malignant neoplasm involving the esophagus. "Esophageal cancer specimens exhibit co-overexpression of Wnt2 and Wnt5A, as well as receptors such as FZD2 and FZD6, which are linked to worse prognosis and reduced survival." (PMID 40943055, 2025). "Proliferation of KYSE-70 and TE-11 esophageal cancer cells, in which Wnt5a was expressed at higher levels than in HeLaS3 cells, was also suppressed by knockdown of Wnt5a." (PMID 25622531, 2015). "Wnt5a is known to antagonize β-catenin signaling in esophageal cancer, but in NSCLC expression of Wnt5a appears to increase proliferation." (PMID 22403725, 2012). "Moreover, Wnt5A/FZD-2 signaling could activate Src family kinases (SFKs) and induces cervical, lung, and esophageal cancer cell proliferation." (PMID 33723319, 2021).
fibrosis (7 papers, 2011 to 2026). the formation of excess fibrous connective tissue in an organ or tissue in a reparative or reactive process. "Cardiomyocyte-expressed LRP6 interacted with cathepsin D (CTSD, a protease) and promoted the degradation of Wnt5a and Wnt11, inhibiting cardiac fibrosis and dysfunction induced by TAC." (PMID 33391533, 2021). "In conclusion, pressure overload enhances the secretion of Wnt5a or Wnt11 from CMs and CFs which promotes cardiac fibrosis by activation the crosstalk of FZD5 and EGFR." (PMID 34564708, 2021). "LRP6 overexpression reduced the expression and secretion of Wnt5a and Wnt11 by cardiomyocytes, and knockdown of Wnt5a and Wnt11 greatly inhibited cardiac fibrosis and dysfunction under pressure overload in vitro and in vivo." (PMID 33391533, 2021). "Meflin-deficient mice exacerbated intestinal fibrosis with dysregulated expression of non-canonical Wnt ligand WNT5A and its receptor ROR2." (PMID 42154532, 2026). "The knockdown of Wnt5a and Wnt11 significantly inhibited cardiac fibrosis under pressure overload." (PMID 33391533, 2021). "However, few evidences indicate that Wnt5a or Wnt11 directly promotes cardiac fibrosis during chronic pressure overload." (PMID 34564708, 2021). "Thus, we demonstrate that the Wnt5a expression of SMC of the airways leads to aggravated fibrosis of the lung with poor clinical conditions." (PMID 34451852, 2021). "Therefore, Egr inhibitors and Wnt5a antibodies are potential therapies for treatment of oral submucosal fibrosis and oral cancer." (PMID 33167868, 2020). "Second, we did not use WNT5A deficient animals to prove that target genes of this pathway contribute to the pathogenesis of ventilator-induced fibrosis in VILI." (PMID 21935365, 2011).
Hypertension (7 papers, 2020 to 2022). The presence of chronic increased pressure in the systemic arterial system. "Serum Wnt5a or Wnt11 was elevated and associated with diastolic dysfunction in hypertension patients." (PMID 34564708, 2021). "Inhibition of Wnt5a or Wnt11 may have therapeutic potential for the prevention of cardiac fibrosis associated with hypertension or pressure overload." (PMID 34564708, 2021). "In the present study, we revealed that serum Wnt5a and Wnt11 were increased in patients with hypertension as compared to healthy controls." (PMID 34564708, 2021). "Serum Wnt5a and Wnt11 levels were examined in patients with hypertension (HBP) and the control group." (PMID 34564708, 2021). "Here, we aimed to explore serum Wnt5a and Wnt11 levels in hypertension patients, the roles of Wnt5a and Wnt11 in cardiac fibrosis and potential mechanisms under pressure overload." (PMID 34564708, 2021). "At baseline, obese children with hypertension had lower Sfrp5 and higher Wnt5a concentrations, whereas a reduction of BMI and blood pressure after 6 months resulted in increased Sfrp5 concentrations." (PMID 34371968, 2021). "We then analyzed the relationship between serum Wnt5a or Wnt11 level and echocardiographic parameters of hypertension patients and the control group." (PMID 34564708, 2021). "By activating the non-canonical Wnt5a/RhoA pathway, Klotho deficiency increases salt sensitivity in patients with hypertension which leads to increased total peripheral resistance via vasoconstriction, therefore raising BP." (PMID 36457804, 2022). "Next, we evaluated the implication on SFRP5, WNT5A and PPARγ in SAT and VAT according to metabolic syndrome presence and their components (T2DM, dyslipidaemia and hypertension)." (PMID 36077270, 2022). "Accordingly, implementation of a lifestyle intervention program in obese children with hypertension resulted in a rapid decrease in Sfrp5 but no change in Wnt5a concentrations." (PMID 34371968, 2021).
osteoporosis (7 papers, 2020 to 2025). A condition of reduced bone mass, with decreased cortical thickness and a decrease in the number and size of the trabeculae of cancellous bone (but normal chemical composition), resulting in increased fracture incidence. "The scaffold's ability to upregulate Wnt4, Wnt5a, and Wnt10b expression enhances osteogenic differentiation, reversing the Wnt inhibition characteristic of osteoporosis." (PMID 41542097, 2025). "Quantitative real-time PCR shown that Wnt1, Wnt5a, Wnt7a, and Wnt9a mRNAs were lower expressed in osteoporosis derived EVs, while DKK mRNA was up regulated in osteoporosis compared to non-osteoporotic individuals." (PMID 34375951, 2021). "Quantitative real-time PCR shown that Wnt1, Wnt5a, Wnt7a, and Wnt9a mRNAs were lower expressed in osteoporosis derived EVs." (PMID 34375951, 2021). "In osteoporosis studies, miR-16-2-3p was found to target and regulate WNT5A expression." (PMID 39881385, 2025). "Our study suggests targeting Wnt5a could be a promising strategy for enhancing bone regeneration in post‐menopausal osteoporosis." (PMID 39288944, 2025). "Our data reveled that Ps-GOS significantly up-regulates the expression of Wnt5a, LRP5, β-catenin, and Fzd4 mRNA, in MC3T3-E1 cells, suggesting that Ps-GOS may prevent bone loss in osteoporosis through Wnt/β-catenin together with BMP-2 signaling pathways." (PMID 32012654, 2020). "In addition, the results of our study demonstrated that the mRNA levels of Wnt1, Wnt5a, Wnt7a, and Wnt9a were lower in osteoporosis-derived EVs than in non-osteoporosis-derived EVs, while DKK mRNA was up-regulated in osteoporotic individuals compared to non-osteoporotic individuals." (PMID 34375951, 2021).
squamous cell carcinoma (7 papers, 2009 to 2022). A carcinoma arising from squamous epithelial cells. "PPARgamma, VEGF-A, Wnt5a, miR-27b and miR-200b levels were determined in resected adenocarcinoma and squamous cell carcinoma samples by qRT-PCR and TaqMan microRNA assay." (PMID 27876017, 2016). "Among the three histological types, Wnt5a was frequently expressed in squamous cell carcinoma (70.89%, 56/79), while Wnt5a-positive expression in adenocarcinoma was the lowest (49.33%, 37/75)." (PMID 24999479, 2014). "Wnt5a was more frequently expressed in squamous cell carcinoma." (PMID 24999479, 2014). "We found a group of tumor-specific WNT members, including a panel of squamous cell carcinomas (SCCs) specific upregulated WNT ligands and receptors, WNT5A, WNT7B, FZD7 and GPC1." (PMID 35850748, 2022). "Wnt5a expression level was upregulated in the majority of NSCLC tissues, especially in squamous cell carcinoma, while its expression level in adenocarcinoma was the lowest." (PMID 24999479, 2014). "In non-responders with squamous cell carcinoma, LAMB3, ITGB8, and WNT5A genes were highly expressed." (PMID 35135489, 2022).
Alzheimer disease (6 papers, 2014 to 2025). A progressive, neurodegenerative disease characterized by loss of function and death of nerve cells in several areas of the brain leading to loss of cognitive function such as memory and language. "In the brown module, the tissue-specific genes PIK3R1 and WNT5A participated in the axon guidance and Alzheimer’s disease." (PMID 36081461, 2022). "The same relationship has been observed in Alzheimer’s disease, where the levels of miR-101b are reduced, but the levels of Wnt-5a are increased." (PMID 26895946, 2016). "Second, COX2 has been related to inflammation, synaptic plasticity and Alzheimer disease, which correspond to biological processes in which Wnt-5a is involved and plays a key role." (PMID 26895946, 2016). "Wnt5a was upregulated in the Alzheimer’s disease mouse brain due to β-amyloid peptide, inducing neuroinflammation and neurotoxicity via inflammatory cytokines IL-1β and TNF-α." (PMID 24993819, 2014). "The genes represented by the age‐DMRs included a few notable members such as Cyp46a1 and Abca7, which are involved in cholesterol metabolism and implicated in Alzheimer's disease, and few members of the WNT signaling and mesenchyme developmental pathways (e.g., Fzd1, Fzd8, Wnt5a, Jak3, Ptk7, Nrp2)." (PMID 32790008, 2020).
bronchopulmonary dysplasia (6 papers, 2020 to 2025). Bronchopulmonary dysplasia is a chronic respiratory disease that results from complications related to lung injury during the treatment of infant acute respiratory distress syndrome in low-birth-weight premature infants or from abnormal lung development in older infants. "Aberrant expression of Wnt5a is also associated with cancerous lung disease, pulmonary fibrosis, bronchopulmonary dysplasia (BPD), and hyperoxia injury." (PMID 40271154, 2025). "Postnatal Wnt5a inactivation disrupted alveologenesis, producing a phenotype resembling human bronchopulmonary dysplasia (BPD)." (PMID 32046118, 2020). "P2 inactivation of Wnt5a disrupted alveologenesis resulting in enlarged alveolar structures, reminiscent of a phenotype characteristic of the human neonatal chronic lung disease known as bronchopulmonary dysplasia (BPD)." (PMID 32046118, 2020). "Lack of Wnt5a results in alveolar insufficiency and modulation of this protein is being actively pursued as a potential treatment for bronchopulmonary dysplasia, a disease of prematurity where alveologenesis is impaired." (PMID 38476262, 2024).
cleft palate (6 papers, 2014 to 2025). Cleft palate is a fissure type embryopathy that affects the soft and hard palate to varying degrees. "It has also been suggested that the Ryk receptor may interact with Ror2 to bind Wnt5a, and mutations in Ryk also cause cleft palate in mice." (PMID 30760477, 2019). "It is possible that conditional Wnt5a LOF may result in heightened vulnerability to cleft palate." (PMID 40777421, 2025).
multiple myeloma (6 papers, 2013 to 2023). "In multiple myeloma, WNT5A mediates the adhesion of myeloma cells to bone marrow cells via a ROR2 and AKT-dependent mechanism." (PMID 36982422, 2023). "In the GSE4204 dataset, our Kaplan-Meier survival analyses demonstrated that low expression of CXCL12 (p-value: 0.009800177) and WNT5A (p-value: 0.012647237) displayed more unfavorable outcomes for multiple myeloma patients." (PMID 34249967, 2021). "Among all dysregulated immune-related mRNAs, AEN, CD320, FABP5, and GPI were risk factors for multiple myeloma, while CXCL12, IGKC, NOD2, VCAM1, and WNT5A were protective factors for multiple myeloma." (PMID 34249967, 2021). "WNT5A is an abundant growth factor upon myeloma bone marrow specimens." (PMID 34249967, 2021). "Although Wnt5a has been reported to promote osteoblastogenesis of human MSCs through Fzd receptors and Ror2, it has been found that myeloma cells in co-culture with pre-OBs inhibit Ror2 expression in the latter, thus impairing osteogenic differentiation and contributing to OB suppression." (PMID 25268740, 2014). "Interestingly, the list includes the gene SLC31A2 a membrane pump involved in resistance to alkylating drugs; FBXW7, USP6, UBE2J1 and Wnt-5a involved in ubiquitin proteasome pathways known to affect myeloma biology." (PMID 24376673, 2013).
myocardial infarction (6 papers, 2020 to 2025). Gross necrosis of the myocardium, as a result of interruption of the blood supply to the area, as in coronary thrombosis. "Wnt5a can promote myocarditis and fibrosis, leading to the deterioration of myocardial remodeling after myocardial infarction." (PMID 40056066, 2025). "In a rat left anterior descending ligation myocardial infarction model, increased protein levels of Wnt5a, Ror2, and Vangl2—one if its immediate downstream targets—were observed in the remote vital area." (PMID 33134326, 2020). "In addition, TGFβ1-SMAD2/3 signaling can improve cardiac repair after myocardial infarction by inducing myocardial fibroblasts to express CTHRC1 and then selectively activate WNT5A signialing pathway." (PMID 37284318, 2023).
renal fibrosis (6 papers, 2014 to 2022). A final common manifestation of a wide variety of chronic kidney diseases characterized by glomerulosclerosis and tubulointerstitial fibrosis. "In a mice model of kidney fibrosis, short hairpin RNA-mediated knockdown of Wnt5a expression reduced renal fibrosis and macrophage M2 polarization." (PMID 36429021, 2022). "And some of these proteins like CTSD, ATF3, Wnt5a were reported play important roles in renal fibrosis or other kidney disease." (PMID 28912732, 2017). "And some of these proteins like CTSD, ATF3, WNT5A were reported play important roles in renal fibrosis or other renal disease." (PMID 28912732, 2017). "Their results showed that Wnt5a stimulates macrophage M2 polarization to promote renal fibrosis." (PMID 36429021, 2022).